KIAA0753 (KIAA0753)
Description:
Involved in centriole duplication. Positively regulates CEP63 centrosomal localization. Required for WDR62 centrosomal localization and promotes the centrosomal localization of CDK2. May play a role in cilium assembly.
Synonyms: MNR; OFIP; JBTS38; SRTD21
Tractability: PROTAC: ubiquitination databases record sites on it.
Gene: Protein-coding gene on chromosome 17 (6,578,147 to 6,640,711, reverse strand). Ensembl gene ENSG00000198920.
Subcellular location: Cytoplasm, cytoskeleton, microtubule organizing center, centrosome, centriole; Cytoplasm, cytoskeleton, microtubule organizing center, centrosome, centriolar satellite; Cytoplasm, cytoskeleton, microtubule organizing center, centrosome
Subcellular location (Human Protein Atlas): Centrosome; Basal body; Cytosol; Primary cilium
Gene Ontology:
Molecular function: protein binding
Biological process: cilium assembly; cytosolic ciliogenesis; protein localization to centrosome; centriole replication
Cellular component: centriolar satellite; centrosome; microtubule organizing center; centriole
Genetic constraint (gnomAD): Loss-of-function variants: 76 observed, 85.86 expected, observed/expected ratio (o/e) 0.89, 90% interval 0.74 to 1.07. The upper end of that interval is the gene's LOEUF score, 1.07, which puts it in group 4 of 6, group 1 being the genes least tolerant of losing a copy. Missense variants: 982 observed, 1,022.9 expected, observed/expected ratio (o/e) 0.96, 90% interval 0.91 to 1.01. Synonymous variants: 345 observed, 365.95 expected, observed/expected ratio (o/e) 0.94, 90% interval 0.86 to 1.03.
Homologues: Orthologues: chimpanzee KIAA0753 (99% identical), rat 4933427D14Rikl (76% identical), mouse 4933427D14Rik (76% identical), guinea pig KIAA0753 (75% identical), rabbit KIAA0753 (75% identical), dog KIAA0753 (60% identical), tropical clawed frog slc13a5 (38% identical), zebrafish si:dkey-243i1.1 (30% identical).
Diseases named in the same sentence as KIAA0753 in open-access papers:
KIAA0753 is named in the same sentence as 15 diseases in open-access papers, as found by Europe PMC text mining. Sharing a sentence is not in itself a finding about the gene and the disease. The quoted sentences say what the papers report.
orofaciodigital syndrome (4 papers, 2017 to 2024). Two syndromes of oral, facial, and digital malformations. "For instance, biallelic variants in CEP120 results in Joubert syndrome 31 and severe short-rib thoracic dysplasia type 13 while spectrum of KIAA0753 related conditions extends to Joubert syndrome 38, orofaciodigital syndrome XV andshort-rib thoracic dysplasia 21without polydactyly." (PMID 38702430, 2024). "Interestingly, mutations in genes encoding for the other two components of the distal centriole complex, MNR/KIAA0753 (OMIM 617112), and OFD1 cause JBTS (MIM 300804) or orofaciodigital syndrome (MIM 311200)." (PMID 34830133, 2021). "Indeed KIAA0753, which falls within our 25% cFDR list of cilium genes, was shown to interact with OFD1 and FOR20 at pericentriolar satellites and centrosomes, and gives rise to oral-facial-digital syndrome, a phenotype associated with disruption in the ciliary transition zone and the basal body." (PMID 31095607, 2019).
diabetes (2 papers, 2020 to 2024). "In summary, we report a negative regulatory relationship between KIAA0753 and diabetes-related bone loss." (PMID 39245790, 2024). "However, the specific contribution of KIAA0753, a primary cilia protein, in bone loss induced by diabetes remains unclear." (PMID 39245790, 2024). "In this investigation, we elucidated the pivotal role of KIAA0753 as a promoter of osteoblast differentiation in diabetes." (PMID 39245790, 2024). "Diabetes mouse models further validated the downregulation of KIAA0753 protein in the femur." (PMID 39245790, 2024). "Additional insights indicated that KIAA0753 effectively restored osteoblast differentiation by directly interacting with SHH, OCN and Gli2, thereby activating the Hedgehog signalling pathway and mitigating the ubiquitination of Gli2 in diabetes." (PMID 39245790, 2024).
Joubert syndrome (2 papers, 2017 to 2024). Joubert syndrome (JS) is characterized by congenital malformation of the brainstem and agenesis or hypoplasia of the cerebellar vermis leading to an abnormal respiratory pattern, nystagmus, hypotonia, ataxia, and delay in achieving motor milestones. "Mutations in the KIAA0753 gene have recently been associated with Joubert syndrome (JBTS) and orofaciodigital (OFD) syndrome." (PMID 29138412, 2017).
brain abnormalities (1 paper, 2017). "Our patients with phenotypic features of skeletal dysplasia and brain abnormalities, together with previously reported patients with milder phenotypes of OFD and JBTS, represent the full phenotype-spectrum of the KIAA0753-related ciliopathy syndrome." (PMID 29138412, 2017).
ciliopathy (1 paper, 2017). A genetic disorder of the cellular cilia or the cilia anchoring structures, the basal bodies, or of ciliary function. "Our study expands the phenotypic variability of the KIAA0753-related conditions and shows the importance of using massive parallel sequencing to achieve the diagnosis in view of the genetic and phenotypic heterogeneity of ciliopathies." (PMID 29138412, 2017). "We used the zebrafish model to confirm the role of kiaa0753 in ciliopathy and skeletal dysplasia." (PMID 29138412, 2017).
Jeune syndrome (1 paper, 2024). Jeune syndrome, also called asphyxiating thoracic dystrophy, is a short-rib dysplasia characterized by a narrow thorax, short limbs and radiological skeletal abnormalities including "trident" aspect of the acetabula and metaphyseal changes. "Asphyxiating thoracic dystrophy (Jeune’s syndrome) may be caused by mutations in ciliary genes such as DYNC2H1, and mutations in DYNC2H1 and in KIAA0753 were present in patients with recurrent respiratory infections." (PMID 38674609, 2024).
cancer (3 papers, 2017 to 2024). A tumor composed of atypical neoplastic, often pleomorphic cells that invade other tissues. "For example, CCDC77 was suggested based on the information on the cancer dependency (DepMap), cancer gene expression, an annotation for the GO term “centriole,” tissue gene expression, and protein interaction with KIAA0753." (PMID 38482491, 2024).
skeletal dysplasia (2 papers, 2017 to 2021). Any Mendelian diseases that affects growth and development of the skeleton. "We report biallelic pathogenic variants in KIAA0753 in four patients with short-rib type skeletal dysplasia." (PMID 29138412, 2017). "In summary, we report severe skeletal dysplasia in four patients with deleterious variants in KIAA0753 and demonstrate expression of KIAA0753 in the growth plate of a normal human fetus." (PMID 29138412, 2017). "We report, for the first time, that mutations in the KIAA0753 gene cause skeletal dysplasia with narrow thorax and metaphyseal widening with limb bowing." (PMID 29138412, 2017). "Almost 20 ciliary genes are associated with skeletal dysplasias, and biallelic variants in other ciliary genes (ALMS1, IFT172, and KIAA0753) have been discovered in individuals with growth hormone deficiency." (PMID 34194391, 2021). "Our patients with skeletal abnormalities seem to be the most severe end of KIAA0753-related congenital syndrome with combination of skeletal dysplasia and JBTS." (PMID 29138412, 2017). "Residual KIAA0753 expression may explain milder skeletal abnormalities as in OFD syndrome, compared to more severe skeletal dysplasia features in our patients." (PMID 29138412, 2017). "We propose that KIAA0753-related syndrome spectrum is a phenotypic continuum from lethal skeletal dysplasia and JBTS features at the most severe end, through non-lethal metaphyseal skeletal dysplasia with short ribs and OFD to JBTS only at the mildest phenotypic end of the spectrum." (PMID 29138412, 2017).
KIAA0753 also shares sentences with these, for which no sentence is quoted: Anxiety (1 paper); anxiety disorder (1); developmental disability (1); Joubert syndrome 38 (1); Nephropathy (1); Obesity (1); prostate carcinoma (1).